AFP (alpha fetoprotein)
Diseases named in the same sentence as AFP in open-access papers (continued):
Sharing a sentence is not in itself a finding about the gene and the disease.
tumor (continued). "Moreover, two nomograms comprising WWOX, AFP, tumor size, and γ‐GT were designed, and showed enhanced prognostic accuracy when compared to conventional staging systems, such as child classification, TNM stage and BCLC stage for OS and RFS in terms of C‐index and clinical net benefit on DCA." (PMID 29905011, 2018). "Furthermore, we determined the association of HPC marker expression profiles and HCC malignancy based on serum levels of tumour markers AFP and AFP-L3, and assessed the potential of AFP and AFP-L3 to predict the expression of HPC markers as an alternative non-invasive approach." (PMID 29774107, 2018). "This case indicates that in some patients, biomarkers aberrantly expressed by their tumors, such as AFP in this patient, may be used as a tumor marker for response to anti-PD-1 therapy and emphasizes the importance of confirming potential escape lesions by pathologic examination." (PMID 30208947, 2018). "Supporting the premise that aggressive tumor biology leads to worse clinicaloutcomes, we also found the LEE_LIVER_CANCER_SURVIVAL_DN gene signature (comprisedof genes highly expressed in HCC associated with poor survival), to be significantly enriched inthe high AFP class of tumors from our study." (PMID 29376136, 2018). "In summary, the authors concluded that the presence of AFP mRNA in peripheral blood may be a useful marker of circulating malignant hepatocytes, which might be used to predict the hematogenous metastatic spread of tumor cells in patients with HCC." (PMID 30176913, 2018). "Finally, by Cox proportional hazards model analysis, it was found that the serum iron levels <15.1 μmol/l was a significant risk factor for the survival of HBV- related HCC (HR = 2.28, 95%CI, 1.82–2.87; P < 0.001) together with higher AFP levels, larger tumor size and worse BCLC stages." (PMID 29467672, 2018). "Alpha-fetoprotein level (AFP) was an independent predictor of survival in our analysis, which is in accordance with the majority of publications, since AFP may be a surrogate marker for tumour burden and tumour aggressiveness." (PMID 29703174, 2018). "Results showed that tumor size (HR = 1.36, 95% CI 1.12–1.65, P = 0.002), albumin levels (HR = 0.76, 95% CI 0.65–0.91, P = 0.002), PT (HR = 2.18, 95% CI 1.54–3.10, P = 0.0001), and AFP levels (HR = 1.13, 95% CI 1.00–1.26, P = 0.049) were independently associated with mortality after RFA for HCC." (PMID 28679433, 2017). "In addition, IL-21 augments rapamycin in the expansion of AFP-specific Tscm cells and therefore these two agents may have an increased potential for tumor immunotherapy when applied concurrently." (PMID 28904691, 2017). "Also, digestive system cancers patients with large tumor size, positive lymph node metastasis, advanced clinical stage, and high AFP level may benefit most from HK2 evaluation to make clinical decisions." (PMID 28415659, 2017). "Therefore, a universal definition of AFP response or AFP change to predict the prognosis after treatment for various treatment modalities and different tumor stage may be impossible." (PMID 29156744, 2017). "Thus, therapeutic approaches that antagonize the effects of tumor-derived AFP may be necessary to enhance antitumor immunity." (PMID 28716068, 2017). "Moreover, our data indicated that high expression of NPAS2 was significantly associated with high AFP and larger tumor size, implying that NPAS2 may have a tumor-promoting role in HCC." (PMID 28333141, 2017). "Furthermore, regarding the association between TACE and sorafenib combination and reduced overall mortality risk, statistical significance was reached in some subgroups (age >60 years, male sex, BCLC stage A or B, Child–Pugh class A5, tumor size >3 cm, AFP ≤200 ng/mL, and tumor response CR and PR)." (PMID 28906355, 2017).
tumor (continued). "Furthermore, we revealed that multiple DELs, including NONHSAT003823, NONHSAT056213, NONHSAT015386 and especially NONHSAT122051, were remarkably correlated with tumor cell differentiation, portal vein tumor thrombosis, and serum or tissue alpha fetoprotein levels." (PMID 29061191, 2017). "Multivariable analysis revealed that tumor recurrence was associated with larger tumor size (HR=1.30 (95% CI: 1.04-1.63), p=0.022), higher serum HBV DNA level (HR=1.11 (95% CI: 1.03-1.20), p=0.005), and serum AFP level ≥20 ng/mL (HR=1.66 (95% CI: 1.17-2.36), p=0.005)." (PMID 27329596, 2016). "Another study demonstrated that serum MDK is elevated in most HCC and may have a diagnostic role in AFP-negative and early stage tumours." (PMID 27219517, 2016). "Thus it was quite possible that increased LDH level was accompanied by the elevation of AFP level and advanced T category, as the augment of tumor burden might upgrade the anaerobic metabolism of the tumor tissue." (PMID 27880930, 2016). "Furthermore, we examined the trends in the relationships between the Liver Scores and the individual components of the Aggressiveness Index and found that for each of MTD, PVT, multifocality and AFP, there was a significant trend between the Liver Index score and the tumor parameter measures." (PMID 28580457, 2016). "HMGB1 not only increased cyclin D1 and PCNA to induce the proliferation of HCC, but also regulates for tumor multiplicity and size, alpha-fetoprotein (AFP) level and advanced TNM stage in HCC, indicating HMGB1 could be used as a biomarker for HCC diagnosis which deserves further study." (PMID 26393575, 2015). "Thus, a serum AFP concentration of 400 μg/L was applied as a boundary point in the current study and revealed that patients with a lower AFP concentration and CK-19+ tumor tissues were more likely to experience a poor prognosis, including both early recurrence and distant metastasis." (PMID 26588210, 2015). "Therefore, in 2008, Hangzhou criteria was proposed to further help to choose the candidates for LT: (a) total tumor diameter less than or equal to 8 cm; or (b) total tumor diameter more than 8 cm, with histopathologic grade I or II and preoperative AFP level less than or equal to 400 ng/mL." (PMID 26658912, 2015). "In addition they demonstrated that combining miR-16 with AFP and Lens culinaris agglutinin-reactive AFP (AFP-L3) tumor markers could increase sensitivity and specificityin the diagnosisofHCC." (PMID 26284247, 2015). "Univariate analysis showed that significant risk factors associated with early recurrence were serum AFP > 400 ng/mL, tumor diameter > 5 cm, the absence of tumor capsules, vascular invasion, multiple tumors, an advanced TNM stage, and occurrence of postoperative complications." (PMID 26466573, 2015). "Furthermore, the miRNA classifier could accurately identify 97.8% HCC cases from both tumor-node-metastasis stages I and II, whereas serum AFP (cut-off level at 20 ng/mL) could only detect 48.9% of the same cases." (PMID 25688372, 2015). "Although AFP has been well known as the “gold standard” among tumor-specific molecular biomarkers since the 1970s, whether intracellular AFP serves as a regulator associated with modulating HCC invasion and metastasis still unclear has not been investigated until now." (PMID 25815363, 2015). "Measurement of AFP is useful for detecting recurrence and for predicting survival after locoregional or systemic treatment, based on the hypothesis of the correlation between AFP level and tumor activity or tumor burden." (PMID 26681337, 2015). "However, Notch3 and AFP co-existed in only a subset of the tumor cell population." (PMID 25668819, 2015). "Thus, combinatorial methods may aid in improving the reliability of HCC prognostic assessments when coupled with low AFP concentrations and consistent Ki-67 index results, which reflect tumor proliferation." (PMID 26588210, 2015).
tumor (continued). "Elevation of serum AFP may be a clue leading to the diagnosis of this tumor; however, preoperative diagnosis is still challenging since there is no characteristic clinical features and, therefore, diagnosis is usually made based on specific histological findings after resection." (PMID 25986692, 2015). "The univariate analysis showed that unfavourable disease-free survival was associated with larger tumour size, poorer histological differentiation, tumour multiplicity, the presence of vascular invasion, advanced tumour stages (AJCC, BCLC, CLIP, CUPI, and JIS), and serum AFP ≥500 μg/l." (PMID 25737613, 2015). "We also observed the strong interactions between SNP rs2057482 and stage, differentiation or AFP levels on prognosis prediction, which suggests that there might be potential modulating roles of these clinical elements representing tumor progression in biological functions of SNP rs2057482." (PMID 26115041, 2015). "This may be easily performed with already established tumor markers, such as AFP and DCP." (PMID 27335840, 2014). "Multivariate analyses revealed that LOH on ZDHHC2 could predict the risk of HCC early recurrence together with AFP level, tumor size, and PVTT but was not an independent prognostic factor." (PMID 24995331, 2014). "Univariate analysis identified the following ten variables that might contribute to postoperative survival of HCC patients: Platelet count, ALT, AST, AFP, tumor size, multiple lesions, tumor capsule absence, BDI of B1, portal vein invasion, and intraoperative blood transfusion (P < 0.05, resp)." (PMID 24723944, 2014). "We then assessed whether tumor sizing was influencing serum AFP concentration." (PMID 25502816, 2014). "In addition, high NLR was significantly correlated with the presence of vascular invasion (OR = 2.69, 95% CI: 2.01–3.59, P = 0.000), tumor multifocality (OR = 1.74, 95% CI: 1.30–2.34, P = 0.000) and higher incidence of AFP ≥ 400 ng/ml (OR = 1.46, 95% CI: 1.01–2.09, P = 0.04)." (PMID 24559042, 2014). "Therefore, serum miR-183 may be used in the diagnosis of HCC, and combined together with other tumor markers, such as AFP, it might improve the sensitivity and specificity." (PMID 24222732, 2013). "Previous studies have also shown that AFP could dimerize with other proteins, such as nuclear receptors (i.e., retinoic receptor), transcription factors and caspases, all of which can promote growth of tumor cells." (PMID 23382965, 2013). "Therefore, the elevated PIVKA-II levels seen after administration of sorafenib may indicate not only tumor progression but also tumor responsiveness, and caution must be exercised when interpreting changes in AFP and PIVKA-II levels together." (PMID 24455683, 2013). "The results of the current study show that age, AFP level, tumor size, ascites, and tumor thrombus may correlate with the prognosis of HCC patients, and should probably be taken into account together with the Child-Pugh classification when considering prognosis." (PMID 23552472, 2013). "Furthermore, PLK4 expression and those clinicopathologic variables significant in univariate analysis (i.e., serum AFP level, tumor size, tumor multiplicity, tumor differentiation, clinical stage and vascular invasion) were further evaluated in multivariate analysis." (PMID 22829937, 2012). "In addition, the serum AFP level is correlated with the tumor size." (PMID 22690340, 2012). "This translates to distinct clinical/genetic profiles for pediatric and adult GCTs, and, especially in cases of AFP wherein these serum levels are developmentally regulated, highlights the significant role of the age of patients in determining normal baseline serum levels of some tumor markers." (PMID 22312308, 2012). "Moreover, the AFP-DCs also exhibited a more potent tumor-specific CTL response." (PMID 23170121, 2012). "Unidentified tumor-specific antigens more immunogenic than PSA or AFP may also exist." (PMID 23112956, 2012).
tumor (continued). "Notably, tumor factors, including tumor size, histological grade, and alpha-fetoprotein levels, have been reported to not be significant risk factors for multicentric recurrence." (PMID 23132957, 2012). "Recent studies indicate that some other tumor markers, such as glypican 3, gamma-glutamyl transferase II, alpha-1-fucosidase, vascular endothelial growth factor, and transforming growth factor-beta 1 could serve as a complementary marker for AFP." (PMID 22957256, 2012). "Analysis of the expression of AFP during liver development in rodent and human embryos is of special interest because this protein is present only in very small amounts in the adult liver, but expressed in relatively large quantities during hepatocarcinogenesis and in most neoplasms." (PMID 21573244, 2011). "However, ZBTB20 and AFP expression, both of tumor tissue origin, were really inversely related." (PMID 21702992, 2011). "Importantly, Aurora B mRNA expression correlated with major clinicopathologic parameters related to tumor progression by univariate analyses, including high AFP level (P < 0.0001), large tumor size (P = 0.021), higher tumor grade (P = 0.0007), and higher tumor stage (P < 0.0001)." (PMID 20799978, 2010). "Based on the association between CIMP status and clinicopathological parameters such as AFP level and tumor numbers, we speculated that the CIMP might be correlated to Hangzhou criteria, which is a new criteria for patient selection and prognosis prediction of LT in HCC patients." (PMID 20678188, 2010). "Conventional serum tumour markers include lactate dehydrogenase (LDH), alpha‐fetoprotein (AFP) and the β‐subunit of human choriogonadotropin (β‐hCG), as well as more recently detected microRNAs." (PMID 41384700, 2026). "Double-ICI combinations and multi-modality regimens remain limited, with ctDNA, bTMB, IL-6 and AFP, CTC, ctDNA emerging as predictors, underscoring the broad applicability of tumor-related markers." (PMID 41535994, 2026). "The concomitant elevation of tumor markers CEA, CA 19-9, and AFP further supported the diagnosis of hepatic malignancy." (PMID 41497147, 2026). "CECT A + P exhibited a large hepatic mass with pulmonary metastases, elevated tumor markers (CEA, CA 19-9, AFP), and normal adrenal glands." (PMID 41497147, 2026). "Preoperative serum levels of osteopontin, galectin-7, and established tumor markers (CA-125, CA19-9, CA15-3, CEA, AFP) were analyzed." (PMID 41899101, 2026). "AFP is a specific biomarker for PLC, and its levels are closely related to tumor burden and treatment efficacy." (PMID 41517800, 2026). "In HCC, elevated TGM2 expression correlates with poor differentiation, high levels of the HCC marker alpha-fetoprotein (AFP), and advanced tumor stage, with pharmacological inhibition of serotonylation suppressing tumor growth." (PMID 41424854, 2026). "LASSO regression screened out 10 key prognostic factors: aspartate aminotransferase, total bilirubin, albumin (ALB), white blood cell count, DD, alpha-fetoprotein, CD4+ T cell count, PVTT, tumor number (≥3) and lymph node invasion." (PMID 42109683, 2026). "In the univariate analysis, mALBI grade 3, tumour size > 4.5 cm, BCLC stage C, treatment line and alpha‐fetoprotein level > 317.5 ng/mL were identified as factors contributing to OS." (PMID 41312615, 2026). "Key factors associated with improved survival included fewer than three lesions, AFP <500 ng/ml, KPS ≥70, and total gross tumor volume (GTV) <40 mL." (PMID 41647833, 2026). "Based on our experience, we suggest annual abdominal and pelvic ultrasound in female patients starting from childhood and, if necessary, MRI, tumor markers (CA-125, BHCG, AFP, and LDH) and a gynecological consult." (PMID 40370432, 2025). "Baseline clinical data, laboratory parameters, and tumor markers (CEA, CA19-9, CA72-4, AFP) were recorded." (PMID 40299527, 2025).
tumor (continued). "Serum tumor markers including, lactate dehydrogenase (LDH), alpha-fetoprotein (AFP), carcinoembryonic antigen (CEA), cancer antigen 125 (CA-125), and carbohydrate antigen 19-9 (CA-19.9) were normal." (PMID 40356778, 2025). "AFP is a glycoprotein produced during fetal development, which is re-expressed in HCC, often indicating aggressive disease biology and greater tumor burden." (PMID 40308490, 2025). "Although AFP and DCP are widely used tumor markers in HCC, the biological mechanisms linking their early elevation to resistance against immune checkpoint blockades remain incompletely understood." (PMID 41463142, 2025). "In the LT cohort, tumor number, platelet count, and PIVKA-II, creatinine, AFP, and total bilirubin levels were key factors." (PMID 40960824, 2025). "AFP levels were positively correlated with NPC1 protein levels (r = 0.353, p = 0.030) and tumor size (r = 0.316, p = 0.015) but negatively correlated with tumor inflammation (r = −0.294, p = 0.029)." (PMID 40722778, 2025). "Furthermore, patients’ clinical characteristics such as tumor stage and alpha-fetoprotein levels, severity of AEs, reasons for treatment discontinuation, and physicians’ rationales for dosage decisions are not available and thus, could not be described for each cohort." (PMID 40795838, 2025). "In multivariate analysis at both time points, BMD remained an independent predictor of survival, alongside tumor growth pattern, therapy, and Albumin-Bilirubin (ALBI) grade (alpha-fetoprotein reached significance only at time of PVTT diagnosis)." (PMID 40845067, 2025). "The levels of tumor markers CA125 and CA19-9 in serum were elevated, while serum carcinoembryonic antigen (CEA) and alpha-fetoprotein (AFP) levels were normal." (PMID 41244785, 2025). "In HCC, BsAbs are designed to target overexpressed TAAs, such as Glypican-3 and alpha-fetoprotein (AFP), to achieve tumor-specific recognition." (PMID 40918452, 2025). "The sensitivity of the double-labeled panel to stage I HCC was 78.26%, higher than that of alpha-fetoprotein (AFP) 47.83%, and the sensitivity to a single tumor (size ≤ 3cm) was 70.27%." (PMID 40500793, 2025). "Early tumor shrinkage was accompanied by changes in CD90(+) and EpCAM(+) CTC counts, whereas AFP and DCP remained largely unchanged." (PMID 40940925, 2025). "Pre-operative variables (drawn ≤ 14 days before surgery) comprised CA19-9, CEA, AFP, CA-125, neutrophil-to-lymphocyte ratio (NLR), γ-glutamyl-transferase (γ-GT), albumin, maximum tumor diameter, and lesion multiplicity." (PMID 41331584, 2025). "Recently, several studies have been conducted to evaluate the role of common tumor markers CEA, CA19-9, CA-125 and AFP in the diagnosis, prognosis and postoperative recurrence detection of patients with CRLMs 11-13,15,16." (PMID 39898242, 2025). "Serum tumor markers, including carcinoembryonic antigen (CEA), carbohydrate antigen 19-9 (CA 19-9), cancer antigen-125 (CA-125), and alpha-fetoprotein (AFP), were within normal limits." (PMID 40400834, 2025). "Initially, to analyze the proliferative state and tumor characteristics of the 3D HCC model, the expression levels of PCNA (proliferating cell nuclear antigen), Ki-67 (Kiel 67 antigen), and AFP (Alpha-Fetoprotein) were quantified." (PMID 41008923, 2025). "Serum levels of tumor markers CA 125, CA 19-9, CA 15-3, carcinoembryonic antigen (CEA), alpha-fetoprotein (AFP), and β-human chorionic gonadotropin (β-hCG) were within normal limits." (PMID 40862798, 2025). "Significant differences between the two groups were observed in WBC, AFP, ALBI, tumor size, PVTT, N status, and BCLC stage." (PMID 41458972, 2025). "Another study using a DC vaccine loaded with AFP peptides in combination with a PD-1 inhibitor demonstrated enhanced antigen-specific CTL responses and significant tumor load reduction in patients." (PMID 40432108, 2025).